AFP (alpha fetoprotein)
Diseases named in the same sentence as AFP in open-access papers (continued):
Sharing a sentence is not in itself a finding about the gene and the disease.
germ cell tumor (continued). "The second model list of EDL includes AFP diagnostic testing for the screening of HCC and staging and disease monitoring of germ cell tumors." (PMID 34746648, 2021). "If a pelvic mass is present, RMS should be considered only when a laboratory examination of alpha fetoprotein (AFP) is used to exclude the mass as a germ cell tumor." (PMID 33330062, 2020). "Determination of serum tumor markers, β-HCG and AFP, is important in the diagnosis and follow-up of germ cell tumors." (PMID 33005196, 2020). "Germ cell tumor markers revealed an alpha-fetoprotein of < 2.5 μg/L and a beta-human chorionic gonadotrophin of 2526 IU/L." (PMID 30563561, 2018). "Alpha-fetoprotein and beta-human chorionic gonadotropin in germ-cell tumors provide a remarkable example of accurate CSF indicators capable of shedding light on diagnosis, risk profile and response to therapy." (PMID 28526811, 2017). "The diagnosis of an intracranial germ cell tumor is based on clinical symptoms, the detection of biomarkers such as AFP and B-HCG in blood and cerebrospinal fluid, magnetic resonance imaging of the brain and spinal cord, CSF cytology and histology." (PMID 28612337, 2017). "Previous research has shown that the human T cell repertoire can recognize an AFP peptide as a HLA-A2.1 restricted epitope and is expressed in certain tumors such as hepatocelullar carcinoma and germ cell tumors." (PMID 28904691, 2017). "A needle core biopsy revealed a malignant germ cell tumor, and immunohistochemical staining was positive for AFP." (PMID 28634489, 2017). "Raised serum AFP levels indicate the presence of yolk sac and embryonal elements in mixed germ cell tumours, as seen in our case." (PMID 27807495, 2016). "Germ cell tumors normally present as a painless mass and can be evaluated with ultrasound and serum levels of α-fetoprotein (AFP), human chorionic gonadotropin (hCG), and lactate dehydrogenase (LDH)." (PMID 24592281, 2014). "AFP is also expressed in germ cell tumors, whereas CK-18 is also expressed by accessory glands of the skin, and the epithelial neoplasm of some digestive organs and urocysts." (PMID 24340101, 2013). "Immunohistochemical staining was positive for alpha-fetoprotein suggesting the diagnosis of a germ cell tumor." (PMID 23631464, 2013). "Serum AFP titers also rise in acute or chronic hepatitis, pregnancy and presence of germ cell tumors." (PMID 23840303, 2013). "As for tumor markers, the measurement of serum AFP and β-hCG level is important to exclude secreting germ cell tumors, which were normal in the presented case." (PMID 23424695, 2013). "The only other major class of neoplasms that are AFP positive is germ cell tumors, especially endodermal sinus tumors." (PMID 20062599, 2009). "In differential diagnosis, other AFP-producing gastric tumors as well as a metastasizing germ cell tumor should also be excluded." (PMID 20062620, 2009). "Based on these results and considering the AFP‐producing nature and potential germ cell tumor differentiation, bleomycin, etoposide, and cisplatin (BEP) therapy was initiated 12 months after initial treatment, following the protocol for germ cell tumors (GCTs)." (PMID 40922714, 2025). "Elevated AFP, HCG, and LDH are associated with germ cell tumors like teratomas." (PMID 41170443, 2025). "The combination of imaging features and histopathological examination allows for the exclusion of other diseases that can cause increased levels of alpha-fetoprotein (AFP), such as hepatoblastoma, teratomas containing yolk sac elements, and other germ cell tumors." (PMID 39706145, 2025). "Elevated AFP levels may also suggest the presence of yolk sac tumor components in the context of a mixed germ cell tumor." (PMID 41008884, 2025). "NUT carcinoma is challenging to diagnose and may mimic a germ cell tumor (GCT) due to raised serum alpha-fetoprotein (AFP)." (PMID 40277298, 2025). "The value of hCG and AFP in the diagnosis of germ cell tumors has other pitfalls." (PMID 39420885, 2024).
germ cell tumor (continued). "Although alpha-fetoprotein is a serum tumour marker typically associated with non-seminomatous germ cell tumours, previous reports have noted elevated serum AFP levels in some cases of histologically pure seminomas." (PMID 39461959, 2024). "Serum levels of AFP >10 ng/ml and CSF levels of AFP >2 ng/ml, in the context of an intracranial mass, are considered diagnostic of nongerminomatous germ cell tumors." (PMID 37519792, 2023). "These germ cell tumor subtypes may be differentiated via both histologic features, and commonly with serum tumor markers including AFP, LDH, and hCG." (PMID 37485120, 2023). "In addition, patients with yolk sac tumors or mixed germ cell tumors with yolk sac components presented the highest serum AFP levels." (PMID 37508611, 2023). "Serum AFP may also be elevated by germ cell tumors, viral hepatitis, liver fibrosis, and neurodegenerative diseases such as A-T." (PMID 36941982, 2023). "Similar to CA125, AFP could be applied as a biomarker for treatment effect and recurrence of germ cell tumors." (PMID 36553184, 2022). "With respect to clinical practice, the very low expression rates of bHCG and AFP (<10%) observed in the smallest tumour size category of germ cell tumours underscore the limited usefulness of the classical tumour markers for diagnosing subcentimeter testicular neoplasms." (PMID 36358866, 2022). "AFP is a reliable biomarker to distinguish malignant germ cell tumors from benign ovarian lesions." (PMID 36553184, 2022). "The 2 main markers produced by germ cell tumors are AFP and β-HCG." (PMID 34232179, 2021). "Germ cell tumors maintain the molecular profile of their primordial lineage as they retain the expression of embryonic proteins, such as beta-human chorionic gonadotropin (bHCG) and alpha-fetoprotein (AFP)." (PMID 33925295, 2021). "Finally, AFP mainly synthesized by the foetal yolk sac and liver during embryonic development is a marker for germ cell tumours." (PMID 32372544, 2020). "In patients for whom a diagnosis of germ cell tumor is suspected, the standard approach has been to obtain intracranial imaging, to sample serum and cerebral spinal fluid (CSF) for tumor markers (AFP and bHCG), and to have baseline endocrine and ophthalmologic evaluations." (PMID 32943645, 2020). "Production of AFP in tumors us often found in the germ cell tumors, particularly yolk sac tumor." (PMID 29933751, 2018). "Because yolk sac tumors are the most common malignant germ cell tumors in children, and AFP is elevated in >90% of pediatric yolk sac tumors, it is important to note that serum AFP levels in infants are normally higher than those in adults and reduce to normal levels by the age of 1." (PMID 28347316, 2017). "Besides, there are several independent factors that predict poor survival include persistent germ cell tumour in residual mass, sarcoma degeneration, and postchemotherapy AFP level greater than 1001 ng/mL." (PMID 27807495, 2016). "OCT-3/4, CD-30 and AFP are markers of various germ cell tumors." (PMID 21108779, 2010). "Human chorionic gonadotropin (hCG), alpha-fetoprotein (AFP), and lactate dehydrogenase (LDH) are serum tumor markers (STMs) that play a clear role in diagnosis, staging, risk classification, and clinical management of testicular germ cell tumors." (PMID 19709439, 2009). "Notably, elevated AFP levels are highly specific for malignant germ cell tumors." (PMID 41000187, 2025). "The determination of Human Chorionic Gonadotropin (hCG) and Alpha Fetoprotein (AFP) levels on serum and amniotic fluid plays a fundamental role in the diagnosis and follow-up of specific physiological or pathological conditions (e.g., pregnancy, threat of abortion or germ cell tumors)." (PMID 34829327, 2021). "However, high AFP expression may be detected in certain pathological conditions, such as deterioration of chronic liver disease, pregnancy, and the presence of germ cell tumors or gastric cancer." (PMID 34834495, 2021).
germ cell tumor (continued). "However, AFP may also be expressed in certain pathological conditions, including chronic liver diseases, germ cell tumors, and gastric cancer." (PMID 31590436, 2019). "Germ cell tumors may secrete detectable levels of proteins into the blood and/or cerebrospinal fluid (CSF), and beta-human chorionic gonadotropin (HCG) and alpha-fetoprotein (AFP) are used for diagnostic purposes and monitor tumor recurrence." (PMID 27239400, 2016). "In addition, tests for both AFP and human chorionic gonadotropin (hCG) have been helpful in reducing clinical staging errors in patients with some testicular tumors and aid in the differential diagnosis of various germ cell tumors." (PMID 28788700, 2014). "In standard clinical practice, the determination of the concentrations of the alpha-fetoprotein (AFP) and beta subunit of human chorionic gonadotropin (β-HCG) are the primary biochemical tumor markers utilized for diagnosing rare pediatric germ cell tumors." (PMID 41399659, 2026). "This study underscores the diagnostic and prognostic importance of both classical serum tumor markers (AFP, β-HCG, and LDH) and hematological indices (NLR, MPV/PLT, and PLT×NLR) in patients with germ cell tumors." (PMID 41527642, 2025). "In our case, IHC analysis revealed distinctive staining for AFP, supporting the presence of YST in a mixed germ cell tumor." (PMID 40370888, 2025). "Epithelial ovarian tumors typically occur in older women and are often associated with elevated CA125 levels; however, in this case, CA125 was within normal limits, and the significantly elevated AFP and β-HCG supported the diagnosis of a germ cell tumor." (PMID 41018086, 2025). "Tumor markers such as AFP and b-HCG are useful in predicting prognosis for germ cell tumors, with elevated levels indicating immaturity and malignancy." (PMID 41523527, 2025). "Elevated levels of AFP in adults can be found in HCC and other tumor diseases (germ cell tumors, cholangiocarcinoma, and gastric adenocarcinoma)." (PMID 38396674, 2024). "The low elevation of human gonadotropin and the significant increase of AFP and LDH suggest the possibility of malignant germ cell tumor." (PMID 37660086, 2023). "AFP remains the standard marker for YST, even though it can also be produced by several non-germ cell tumors, especially those of the female genital tract, and tumors of endodermal origin with a frequent hepatoid component." (PMID 35027045, 2022). "As an exception, in the clinical setting of elevated CSF concentration of AFP and/or β-HCG in the combination with a typical radiological appearance of a germ cell tumor on MRI, histological confirmation can be omitted and treatment initiated without biopsy." (PMID 32504201, 2021). "Of those, two patients with elevated CSF levels of AFP and β-HCG were histologically diagnosed as malignant teratoma and mixed malignant germ cell tumor, respectively." (PMID 32504201, 2021). "A study conducted on 80 germ cell tumours revealed a sensitivity of 78.9% and a specificity of 96.6% for CSF tumour markers (with a cut-off of 50 IU/L for ß-HCG and 25 ng/mL for AFP)." (PMID 34357128, 2021). "Well established serum tumor markers (STMs) for guiding the management of patients with germ cell tumors include human chorionic gonadotropin (HCG), α-fetoprotein (AFP), and lactate dehydrogenase (LDH)." (PMID 32210101, 2020). "For germ cell tumours, a specific panel should be considered, such as PLAP, alpha-fetoprotein, or OCT 3/4." (PMID 29808414, 2018). "Germ cell tumor markers like lactate-dehydrogenase (LDH), alpha-fetoprotein (AFP), and β-human chorionic gonadotropin (β-HCG) levels were within normal limits." (PMID 26101678, 2015). "In the pre-operative workup, the dosages of serum markers AFP, HCG, AMH, beta HCG, and LDH are useful because the germ cell tumors are produced by them." (PMID 24982844, 2014).
germ cell tumor (continued). "As part of surveillance protocols for stage I germ cell tumours, many centres routinely measure human chorionic gonadotrophin (HCG), alpha feto-protein (AFP) as well as lactate dehydrogenase (LDH)." (PMID 16622461, 2006). "A malignant germ cell neoplasm was considered unlikely and ruled out based on negative AFP and beta-HCG testing and the patient’s age." (PMID 41438665, 2026). "Laboratory studies demonstrated markedly elevated alpha-fetoprotein (AFP) (>60,500 ng/mL), neuron-specific enolase (NSE) (63.8 ng/mL), and lactate dehydrogenase (LDH) (575 U/L), which were suggestive of a germ cell tumor with comprehensive reference to clinical manifestations and imaging findings." (PMID 42137572, 2026). "Notably, many commonly encountered embryonic germ cell tumor markers, including OCT3/4, PLAP, alpha-fetoprotein, human chorionic gonadotropin-B, CD30, and transcriptional activator 2 years, exhibited negative expression patterns in ST." (PMID 40832615, 2025). "But normal AFP and beta hCG levels ruled out germ cell tumour, and the histology was not suggestive of lymphoma." (PMID 41487759, 2025). "However, in germ cell tumors, only a limited number of prospective cohort studies have confirmed the role of β-HCG and AFP in monitoring treatment response and predicting prognosis." (PMID 39958339, 2025). "Depending on the age of the patient, germ cell tumors can also come into differential diagnosis, especially yolk sac tumors, in which case SALL4 negativity favors SLCT, but one has to remember that focal AFP expression is common in SLCT." (PMID 39592485, 2025). "The absence of elevated AFP and β-hCG can help to rule out other GCTs (germ cell tumors) and guide treatment decisions." (PMID 40142802, 2025). "A large cohort study of approximately 1500 patients with testicular cancer revealed that over 60% of individuals with nonseminomatous germ cell tumors exhibited elevated AFP levels." (PMID 40430002, 2025). "Up to 90% of non-seminomatous germ cell tumors have elevated AFP or β-hCG at diagnosis, with 39% having an increased level of both." (PMID 38674232, 2024). "AFP is a key tumor marker in non-seminomatous germ cell tumors and correlates with disease burden and response to therapy." (PMID 39171067, 2024). "In contrast, markers specific to germ-cell tumors like placental alkaline phosphatase and alpha-fetoprotein are negative." (PMID 39677208, 2024). "The patient achieved a complete response: all metastatic lesions disappeared on computed tomography (CT) imaging, AFP levels normalized after treatment, and no further treatment for the germ-cell tumor was required." (PMID 38961474, 2024). "Laboratory tests showed elevated alpha-fetoprotein and lactate dehydrogenase levels, supporting a diagnosis of advanced non-seminomatous germ cell tumor." (PMID 39171067, 2024). "Focal AFP staining is common in SLCT, which complicates differentiating it from germ cell tumors." (PMID 39336518, 2024). "When serum AFP is elevated and a patient does not have explainable liver or germ cell tumors, a search for RCC is recommended." (PMID 37781207, 2023). "Serum AFP is widely used in the diagnosis of HCC and germ cell tumors." (PMID 36673043, 2023). "Beta-human chorionic gonadotropin (HCG) and alpha-fetoprotein (AFP) tumor markers were negative, decreasing the likelihood of testicular germ cell tumors." (PMID 37383304, 2023). "The inverse association of marker expression rates with age is probably related to the predominance of AFP- and bHCG-producing nonseminomatous germ cell tumors in the younger age categories." (PMID 36869885, 2023). "According to our data, AFP is not a relatively reliable biomarker of pregnant patients with germ cell tumors." (PMID 36556136, 2022). "Expression of AFP is typically upregulated in nonseminomatous germ cell tumors and expectedly was not expressed in our fresh testis cell samples." (PMID 34831039, 2021).
germ cell tumor (continued). "A consensus emerged that surgical biopsy was required for intracranial germ-cell tumor diagnosis without elevated AFP or HCG, regardless of radiological imaging findings." (PMID 34858336, 2021). "Unlike in germ cell tumors, where elevations of tumor markers (AFP, hCG, and LDH) allow for staging and determination of treatment regimen, no known marker exists in TS." (PMID 33732643, 2021). "Our data do not support the use of germ-cell tumor markers such as AFP, HCG, LDH during the follow-up of tGrCT patients." (PMID 32719989, 2020). "In particular, in presence of a mediastinal mass in a young man, alpha-fetoprotein elevation is considered nearly pathognomonic of a non-seminoma germ-cell tumor." (PMID 28407756, 2017). "We present the case of a young male with NMC arising in the mediastinum with elevated serum alpha-fetoprotein levels suggestive of an extragonadal nonseminomatous germ-cell tumor." (PMID 27855672, 2016). "Tumour markers are frequently elevated in germ cell tumours, namely, LDH, AFP, and beta-HCG." (PMID 27807495, 2016). "Nonseminomatous germ cell tumor was suspected due to the young age, location of the tumors, and elevated serum alpha-fetoprotein." (PMID 27855672, 2016). "Patients with a primary pure seminoma in the testis who have elevated serum alpha-fetoprotein are rare and should be treated as patients with nonseminomatous germ cell tumors." (PMID 27150447, 2016). "Thus N-cadherin expression correlates with the expression pattern of immunohistochemical markers of malignant germ cell tumours such as CD117, PLAP and AFP." (PMID 23066729, 2012). "The third patient was a 38-year-old male, who, 11 years previously, had a right orchiectomy for a testicular germ cell tumor, no chemotherapy and was under clinical surveillance, normal alpha fetoprotein level and HCG level was <2 IU/L." (PMID 22778538, 2012). "It is well known that elevated AFP and CA-125 levels are seen in non-seminomatous germ cell tumors and ovarian carcinomas, respectively." (PMID 21108779, 2010). "The levels of serologic tumor markers (hCG and AFP) have a high correlation with the presence or absence of residual malignant germ-cell tumor components." (PMID 19893950, 2009). "If these diagnoses are not suspected, assessing alpha-fetoprotein and beta-human chorionic gonadotropin levels may help evaluate the rare but possible presence of non-seminomatous germ cell tumors." (PMID 40861766, 2025). "Furthermore, serum tumor markers such as hCG, AFP, and LDH help exclude germ cell tumors." (PMID 41445799, 2025). "AFP is also a biomarker for neonatal tumors such as yolk sac and non-seminomatous germ cell tumors." (PMID 39224747, 2024). "AFP levels are generally not raised in seminomas; however, in cases where elevated levels of AFP are detected in pure seminoma, it is imperative to acknowledge and manage it as a non‐seminomatous germ cell tumor." (PMID 38507271, 2024). "Serum alpha-fetoprotein (AFP), beta subunit of human chorionic gonadotropin (β-hCG), and LDH should be executed before and after orchidectomy as they guide the diagnosis of TC and may be indicative of germ cell tumor histology." (PMID 38674232, 2024). "Therefore, upfront surgery with the aim to obtain a tissue-based diagnosis seems to be reasonable in pineal masses negative for germ-cell tumor markers AFP and beta-HCG as well as negative medical history of a trilateral retinoblastoma." (PMID 38253790, 2024). "Consequently, biomarkers commonly used to indicate germ cell tumors, such as serum or cerebrospinal fluid AFP, β-hCG, and LDH, are typically negative." (PMID 39737398, 2024). "Third, confirming whether serum levels of ERBB2 and NRG4 were elevated in these patients was not possible because patients with germ cell tumors, colitis, and acute hepatitis, for which AFP is a false positive, were not included in this study." (PMID 37174100, 2023). "AFP is well-known to be elevated in the setting of patients with nonseminoma germ cell tumors." (PMID 37485120, 2023).